Y_RNA (Y RNA )
Gene: Miscellaneous RNA gene on chromosome 4 (157,064,557 to 157,064,663, forward strand). Ensembl gene ENSG00000252524.
Homologues: Orthologues: chimpanzee Y_RNA (99% identical). Paralogues in human: Y_RNA (80% identical), Y_RNA (79% identical), RNY3P1 (79% identical), RNY3 (78% identical), Y_RNA (78% identical), Y_RNA (77% identical), Y_RNA (76% identical), RNY3P9 (75% identical), Y_RNA (75% identical), RNY3P13 (74% identical), RNY3P14 (74% identical), RNY3P7 (74% identical), and 90 more.